TRIM26 (tripartite motif containing 26)
Description:
E3 ubiquitin-protein ligase which regulates the IFN-beta production and antiviral response downstream of various DNA-encoded pattern-recognition receptors (PRRs). Also plays a central role in determining the response to different forms of oxidative stress by controlling levels of DNA glycosylases NEIL1, NEIL3 and NTH1 that are involved in repair of damaged DNA. Promotes nuclear IRF3 ubiquitination and proteasomal degradation. Bridges together TBK1 and NEMO during the innate response to viral infection leading to the activation of TBK1. Positively regulates LPS-mediated inflammatory innate immune response by catalyzing the 'Lys-11'-linked polyubiquitination of TAB1 to enhance its activation and subsequent NF-kappa-B and MAPK signaling. In a manner independent of its catalytic activity, inhibits WWP2, a SOX2-directed E3 ubiquitin ligase, and thus protects SOX2 from polyubiquitination and proteasomal degradation. Ubiquitinates the histone acetyltransferase protein complex component PHF20 and thereby triggers its degradation in the nucleus after its recruitment by the histone demethylase KDM6B, serving as a scaffold protein. Upon induction by TGF-beta, ubiquitinates the TFIID component TAF7 for proteasomal degradation. Induces ferroptosis by ubiquitinating SLC7A11, a critical protein for lipid reactive oxygen species (ROS) scavenging (By similarity). Inhibits directly hepatitis B virus replication by mediating HBX ubiquitination and subsequent degradation. (Microbial infection) Promotes herpes simplex virus type 2/HHV-2 infection in vaginal epithelial cells by decreasing the nuclear localization of IRF3, the primary mediator of type I interferon activation.
Synonyms: RNF95; ZNF173
Tractability: PROTAC: UniProt records ubiquitination sites on it; ubiquitination databases record sites on it; its protein half-life has been measured.
Gene: Protein-coding gene on chromosome 6 (30,184,446 to 30,213,435, reverse strand). Ensembl gene ENSG00000234127.
Subcellular location: Cytoplasm; Nucleus
Subcellular location (Human Protein Atlas): Cytosol; Nucleoplasm
Pathways (Reactome):
Immune System: Interferon gamma signaling
Gene Ontology:
Molecular function: protein binding; ubiquitin protein ligase activity; zinc ion binding
Biological process: antiviral innate immune response; host-mediated suppression of symbiont invasion; positive regulation of non-canonical NF-kappaB signal transduction; proteasome-mediated ubiquitin-dependent protein catabolic process; protein K11-linked ubiquitination; suppression of viral release by host
Cellular component: cytoplasm; cytosol; nucleoplasm; nucleus
Genetic constraint (gnomAD): Loss-of-function variants: 16 observed, 45.05 expected, observed/expected ratio (o/e) 0.36, 90% interval 0.24 to 0.54. The upper end of that interval is the gene's LOEUF score, 0.54, which puts it in group 2 of 6, group 1 being the genes least tolerant of losing a copy. Missense variants: 437 observed, 673.45 expected, observed/expected ratio (o/e) 0.65, 90% interval 0.6 to 0.7. Synonymous variants: 271 observed, 284.05 expected, observed/expected ratio (o/e) 0.95, 90% interval 0.86 to 1.05.
Homologues: Orthologues: chimpanzee TRIM26 (99% identical), macaque TRIM26 (99% identical), rabbit TRIM26 (95% identical), pig TRIM26 (93% identical), mouse Trim26 (89% identical), rat Trim26 (88% identical), guinea pig TRIM26 (86% identical). Paralogues in human: TRIM10 (36% identical), TRIM15 (32% identical), TRIM21 (32% identical), TRIM27 (29% identical), TRIM39 (29% identical), TRIM11 (28% identical), TRIM41 (28% identical), TRIM58 (28% identical), TRIM4 (27% identical), TRIM7 (27% identical), TRIM69 (26% identical), TRIM38 (25% identical), and 68 more.
Diseases named in the same sentence as TRIM26 in open-access papers:
TRIM26 is named in the same sentence as 74 diseases in open-access papers, as found by Europe PMC text mining. Sharing a sentence is not in itself a finding about the gene and the disease. The quoted sentences say what the papers report.
hepatocellular carcinoma (21 papers, 2017 to 2026). A malignant tumor that arises from hepatocytes. "Initial studies found TRIM26 to be associated with poor outcomes of hepatocellular carcinoma." (PMID 38956921, 2024). "It has been shown that TRIM26 is strongly associated with the onset of hepatocellular carcinoma." (PMID 38956921, 2024). "For example, TRIM26 was reported to be a tumor suppressor in hepatocellular carcinoma (HCC), and its downregulation was associated with a worse prognosis in HCC patients." (PMID 37591850, 2023). "Further experiments revealed that overexpressing TRIM26 in a mouse hepatoma cell line, along with other host factors essential for HCV, increased the efficiency of HCV infection, highlighting TRIM26’s contribution to host tropism." (PMID 39596676, 2024). "In our recent study, we investigated the role of the E3 ubiquitin ligase Tripartite motif-containing protein 26 (TRIM26) in promoting the ubiquitination of β-catenin, ultimately inhibiting the progression of hepatocellular carcinoma." (PMID 38926362, 2024). "TRIM26 has been found to be downregulated in various types of cancers and has been shown to impede the progression of hepatocellular carcinoma." (PMID 38926362, 2024). "TRIM26 specifically has been shown to be downregulated in hepatocellular carcinoma and papillary thyroid carcinoma, but upregulated in bladder cancer." (PMID 36232914, 2022). "TRIM26 functions as a tumor suppressor in hepatocellular carcinoma, papillary thyroid carcinoma, and non-small cell lung cancer, but its role in KIRC awaits future exploration." (PMID 35371994, 2022). "Tripartite motif-containing protein 26 (TRIM26) is an E3 ubiquitin ligase that functions as a tumor suppressor in hepatocellular carcinoma, while little is known about its function in liver fibrosis." (PMID 33869196, 2021). "In 2015, Wang et al46 found that TRIM26 was a novel tumor suppressor gene of hepatocellular carcinoma and its downregulation contributes to worse prognosis." (PMID 29956500, 2018). "TRIM26 expression is commonly reduced in various cancers and promote proliferation, while its overexpression has been shown to impede the proliferation of thyroid cancer cells, bladder cancer, hepatocellular carcinoma, and others." (PMID 38926362, 2024). "Similarly, TRIM26 could also act as a tumor suppressor of hepatocellular carcinoma (HCC), and its downregulation was associated with poor prognosis of HCC." (PMID 38260302, 2024). "The connection between TRIM26 and hepatocellular carcinoma has been explored previously." (PMID 33869196, 2021). "A previous study has showed that TRIM26 may serve as a novel tumor suppressor in hepatocellular carcinoma by regulating multiple metabolism-related pathways." (PMID 33869196, 2021). "Interestingly, it has recently been described that TRIM26 functions as a novel tumour suppressor of hepatocellular carcinoma, and that an siRNA knockdown of TRIM26 promotes cell proliferation and metastasis." (PMID 27924031, 2017). "For example, TRIM26 exhibited decreased expression in hepatocellular carcinoma (HCC) and suppressed cell proliferation and migration." (PMID 38773612, 2024). "Interestingly, there is evidence that TRIM26 may act as a tumor suppressor in hepatocellular carcinoma, although whether this is directly related to its role in regulation of NEIL1 and NTH1 is unclear." (PMID 29610152, 2018). "Our results are in perfect agreement with those of Dr. Gang Song's team, who elegantly demonstrated that USP39 and the E3 ligase TRIM26 balance the level of ZEB1 ubiquitination and thereby determine hepatocellular carcinoma cell proliferation and migration." (PMID 39736693, 2024). "Additional research has revealed TRIM26 to maintain the equilibrium of Zinc-finger E-box-binding homeobox 1 (ZEB1) ubiquitination, thereby regulating the advancement of hepatocellular carcinoma through its interaction with the deubiquitinating enzyme USP39." (PMID 38956921, 2024).
hepatocellular carcinoma (continued). "Our previous studies showed that the deubiquitination enzyme USP39 and the E3 ubiquitin ligase TRIM26 balance the ubiquitination level of ZEB1, thereby determining the progression of hepatocellular carcinoma." (PMID 36707504, 2023). "USP39 and E3 ligase TRIM26 balance the level of ZEB1 ubiquitination, thereby determining the progression of hepatocellular carcinoma." (PMID 36906615, 2023). "Mechanistically, TRIM26 ubiquitinates and targets ZEB1 for degradation, while USP39 deubiquitinates and stabilizes ZEB1 to promote hepatocellular carcinoma (HCC)." (PMID 35454770, 2022). "Moreover, USP39 and TRIM26 balanced the expression of ZEB1 to regulate proliferation and metastasis of hepatocellular carcinoma." (PMID 36582601, 2022). "Moreover, TRIM26 has been indicated in the regulation of ZEB1 protein degradation via ubiquitylation, which alongside USP39, controls the epithelial-to-mesenchymal transition and ultimately the growth of hepatocellular carcinoma cells." (PMID 36232914, 2022). "Moreover, a E3 ligase TRIM26 could promote the degradation of ZEB1 by protein ubiquitination, resulting in the inhibition of cell proliferation and metastasis in hepatocellular carcinoma." (PMID 36512117, 2022).
viral infection (12 papers, 2015 to 2024). "Virus infection induces the nuclear localization of TRIM26, which promotes K48-linked polyubiquitination of activated IRF3 to degrade IRF3 and thereby attenuate IFNβ production." (PMID 34619149, 2021). "As a consequence, TRIM26 transgenic mice showed an impaired ability to inhibit virus replication and were more susceptible to virus infection." (PMID 25763818, 2015). "TRIM26 is known to play an important role in innate immunity, particularly in modulating viral infections." (PMID 39596676, 2024). "The involvement of TRIM26 in viral infections is a subject of debate, and its impact is inconsistently demonstrated in various viral infections or cell cultures." (PMID 38956921, 2024). "First, we have described the structure, expression profile, and localization of TRIM26 in cells, followed by a description of the regulatory role of TRIM26 in immunity, inflammation, and viral infection." (PMID 38956921, 2024). "Further research is needed to fully explore the potential of TRIM26 as a therapeutic target for viral infectious diseases." (PMID 39596676, 2024). "TRIM26 has a role in viral infection by inherently limiting the spread of viral infections and enhancing immunological pathways to aid in the elimination of viruses." (PMID 39596676, 2024). "This review highlights the critical role of TRIM26 in viral infections, where it regulates viral replication and modulates immune responses, though its effects vary with different viruses." (PMID 39596676, 2024). "TRIM26 either directly interacts with viral proteins or modulates immune responses to engage with a viral infection, serving as either a protective or detrimental host factor depending on the circumvent of the viral infection." (PMID 39596676, 2024). "It has been demonstrated that the subcellular localization of TRIM26 correlates with the state of viral infection." (PMID 38956921, 2024). "Although studies of the nine kinds of viral infections have gained insights into how TRIM26 affects viral infections, the precise mechanisms remain to be determined." (PMID 39596676, 2024). "The present review focuses on understanding the mechanisms of TRIM26 during viral infection and its potential future applications." (PMID 39596676, 2024). "Because TRIM26 had been reported to modulate either the host IFN response against virus infections or the functions of viral proteins, we investigated which molecular function was associated with the HBV replication." (PMID 37604854, 2023). "It is important to note that TRIM26 KO cells show an increase in IFN-β production after 24 h of viral infection, whereas the expression of ISGs increased at an earlier stage of 6 h post infection." (PMID 33419081, 2021). "Downstream factors such as IFN- β were also observed to be significantly decreased in TRIM26 transgenic mice following viral infection in vivo." (PMID 33419081, 2021). "Specifically, they suggested that following viral infection, TRIM26 enters the nucleus in order to bind IRF3 leading to its degradation." (PMID 33419081, 2021). "This validates the previously reported effect of viral infection that promoted TRIM26 localization to the nucleus." (PMID 33419081, 2021). "It was shown that viral infection can induce TRIM26 expression, and that by modulating IRF3 and interferon-β this acts as a mechanism to evade the innate immune system." (PMID 27924031, 2017). "HE staining showed that severe infiltration of immune cells and injury were observed in the lungs of TRIM26-Tg mice, compared to that of WT mice after virus infection." (PMID 25763818, 2015). "All together, these data suggested that TRIM26 expression is induced upon viral infection, which also induces the nuclear translocation of TRIM26." (PMID 25763818, 2015). "Using TRIM26 transgenic mice, we demonstrated that overexpression of TRIM26 greatly attenuated IFN-β production in primary peritoneal macrophages after virus infection and TLR activation." (PMID 25763818, 2015).
viral infection (continued). "At the same time, we demonstrated that virus infection increased TRIM26 expression and nuclear translocation, which promoted the ubiquitination and degradation of nuclear IRF3 leading to decreased IFN-β production and antiviral responses." (PMID 25763818, 2015). "Furthermore, TRIM26 employs numerous mechanisms through which it can either negatively or positively affect various viral infections." (PMID 39596676, 2024). "TRIM26 was physically associated with MAVS independent of viral infection and reduced MAVS expression." (PMID 38965634, 2024). "Also, TRIM26 has been reported for its versatile role as both protective and detrimental depending on the circumvents of various viral infections." (PMID 39596676, 2024). "On the one hand, polyinosinic:polycytidylic acid [poly (I: C)] stimulation and viral infection (vesicular stomatitis or porcine reproductive and respiratory syndrome virus) can induce porcine TRIM26 expression, thereby evading the host innate antiviral response by inhibiting IFN-β production." (PMID 38956921, 2024). "Therefore, the role of TRIM26 proteins varies, either being protective or detrimental in different viral infection scenarios, highlighting the importance of dissecting TRIM26’s role in viral infection for potential therapeutic use as an antiviral strategy." (PMID 39596676, 2024). "TRIM26, a member of the tripartite motif (TRIM) protein family, composed of more than 70 members in humans, binds to IRF3 and transfers to the nucleus after virus infection to advance the K48-linked-polyubiquitin degradation of IRF3 in the nucleus." (PMID 35196784, 2022). "Additionally, viral infection promotes the nuclear localisation of the E3 ubiquitin ligase TRIM26, allowing TRIM26 to bind phosphorylated IRF3 in the nucleus and promote its K48-linked ubiquitination and degradation." (PMID 32645843, 2020). "Expression of IFN-β also greatly decreased in TRIM26 transgenic mice after virus infection in vivo." (PMID 25763818, 2015). "TRIM26 was translocated into nucleus after viral infection or TLR stimulation." (PMID 25763818, 2015). "Importantly, virus infection promoted TRIM26 nuclear translocation, which was required for IRF3 degradation." (PMID 25763818, 2015). "Therefore, TRIM26 is involved in the innate immune response against viral infection." (PMID 38956921, 2024). "TRIM26 is localized throughout the cytoplasm when there is no stimulation; however, upon viral infection, a considerable amount of TRIM26 enters the nucleus." (PMID 38956921, 2024). "Recently, tripartite motif 26 (TRIM26), a TRIM family protein, has been shown to be involved in a broad range of biological processes involved in innate immunity, especially in regulating viral infection." (PMID 38965634, 2024). "TRIM26 bound to and induced IRF3 polyubiquitination in nucleus after virus infection." (PMID 25763818, 2015). "TRIM26 and TBK1 are physically associated, regardless of viral infection." (PMID 39596676, 2024). "This may explain why WT IRF3 was degraded without virus infection and the level of total IRF3 was decreased in TRIM26-Tg mice." (PMID 25763818, 2015).